STAT3 (signal transducer and activator of transcription 3)
Diseases named in the same sentence as STAT3 in open-access papers (continued):
Sharing a sentence is not in itself a finding about the gene and the disease.
cancer (continued). "Next, we also examined whether brevilin A inhibited CRC growth because STAT3 also plays a role in cancer cell proliferation and apoptosis." (PMID 37062842, 2023). "The IL-6/JAK/STAT3 pathway plays a key role in the growth and development of many human cancers." (PMID 36839713, 2023). "Aberrant STAT3 signaling was observed in nearly 70% of cancers." (PMID 37365152, 2023). "The proliferation of cancer cells was arrested at the S-phase cell cycle, and the migration of cancer cells was inhibited by the increasing concentration of curcumin, together with the decreasing expressions of STAT3, VEGF, and HIF-1α signaling pathways." (PMID 37333486, 2023). "These, in turn, can reactivate dormant DTC proliferation, renew CD133+ cancer cells and endocrine resistance by IL-6/Notch signaling through the IL-6 receptor gp130/gp80 and activated STAT3, through VEGF via PI3K/Akt signaling, SMAD2 and 3, and the EGFR and ERK pathways." (PMID 37296983, 2023). "STAT3 inhibitors have long been widely used in the treatment of cancers 34-37." (PMID 37151888, 2023). "Additionally, we showed that TNFAIP8, the IL-6 cytokine receptor, and IL-6-activated STAT3 pathway activity increased following FFAR2 reduction in the all cancer group." (PMID 37296861, 2023). "In addition, STAT3 is a required downstream effector of Src to induce podosome structures and related invasive phenotypes, suggesting that Src-STAT3 is one of the signaling pathways mediating cancer progression." (PMID 38102641, 2023). "Cancer cells with activated STAT3 show angiogenesis, inflammation, and metastasis." (PMID 37375411, 2023). "Furthermore, the signal transducer and activator of transcription 3 (STAT3) is a kind of oncogene that can promote the invasion and migration potential of cancer cells." (PMID 37755102, 2023). "Additionally, a hypoxic environment can promote exosome secretion by cancer cells as well as cellular proliferation through STAT3 activation and shortening the mitosis duration." (PMID 37373600, 2023). "The ability to manipulate and target this pathway with STAT3 ND inhibitors might be a valuable approach to enhance antitumor responses in cancer immunotherapy strategies." (PMID 37182134, 2023). "As part of the STAT3 pathway, IL-6 is a multifunctional cytokine produced by many cell types and is conducive to normal development of tissue regeneration, immune response, autoimmunity, and a multitude of cancers." (PMID 38002302, 2023). "Furthermore, direct co-culture with M2 TAMs prompts signal transducer and activator of transcription 3 (STAT3) activation in cancer cells, contributing to increased cancer cell proliferation and progression." (PMID 38201623, 2023). "Among existing FDA approved treatments, hydroxychloroquine (HCQ), a brain-penetrant DMARD, was recently shown to impact the JAK/STAT pathway through the inactivation STAT3 in lung adenocarcinoma cells suggesting a novel pharmacological approach in cancer chemotherapy." (PMID 36577843, 2023). "In consideration of IL-6 as the major cytokine participant in STAT3 activation and its significance in cancer formation and suppressing the antitumor immune response, we further examined the effect of 11c on IL-6-induced STAT3 activation cell lines such as Hela and MB231 cells." (PMID 37103357, 2023). "In cancer cells, IL-6 increases the expression of downstream STAT3 targets." (PMID 37753372, 2023).
cancer (continued). "STAT3 acts as a transcriptional activator that regulates multiple target oncogenes and promotes the proliferation, anti-apoptosis, angiogenesis, metastasis, and chemoresistance of cancer cells." (PMID 37836626, 2023). "Indeed, these molecules are hyper-expressed in most cancer cells and sustain the activation of several pro-survival pathways such as STAT3 and the expression of oncogenes, such as c-Myc." (PMID 38067355, 2023). "Anaplastic lymphoma kinase (ALK) is activated in cancer and initiates downstream STAT3 signaling." (PMID 36875139, 2023). "These treatments downregulated p-STAT3 and sensitized the cancer cells to doxorubicin." (PMID 36902166, 2023). "In a transgenic prostate cancer mouse model, diosgenin could abrogate NF-κB/STAT3 activation, and this action attenuated cancer cell growth and metastasis." (PMID 36678588, 2023). "Additionally, cancer stem cell biomarkers, like STAT3, are being explored for prognosis and patient-specific surveillance markers." (PMID 36902858, 2023). "STAT3 was identified as the major mediator of IL-6-dependent cancer cell proliferation in RCCs." (PMID 37190141, 2023). "Therefore, we performed immune correlation analysis and GSEA to further investigate the mechanism by which activated STAT3 leads to poor cancer prognosis." (PMID 37724127, 2023). "In consequence, we hypothesize that the rs181747 CC genotype affects the binding of PRRX2 to IL-6 and that the generated IL-6 contributes to cancer development and progression via p-STAT3 and facilitates chemotactic movement of immune cells." (PMID 37035153, 2023). "In addition to its established role as a transcription factor in cancer, STAT3 regulates mitochondrion functions." (PMID 37081847, 2023). "These genes modulate STAT3 expression and phosphorylation in cancer pathogenesis." (PMID 37731134, 2023). "Moreover, this interaction is essential for activating the signal transducer and activator of transcription 3 (STAT3), a downstream transcription factor that regulates cancer cell aggressiveness." (PMID 38034403, 2023). "The Jak2/Stat3 pathway is reported to be a key mediator for CSC functions in many kinds of cancers." (PMID 37089712, 2023). "KDF1 was upregulated in LUAD tissues and might contribute to the progression of LUAD by enhancing the proliferation, migration and invasion of LUAD cancer cells via activation of the STAT3 pathway and AKT pathway." (PMID 38137415, 2023). "Persistent STAT3 activation is observed in many cancer tissues." (PMID 37173892, 2023). "We hypothesized the existence of a positive feedback loop between FAP and STAT3, which may have implications for developing new approaches in cancer therapy." (PMID 36825204, 2023). "To date, numerous efforts have been made to target STAT3 pathway for cancer treatment." (PMID 37095176, 2023). "High levels of STAT3 are detected in several types of cancer." (PMID 36760267, 2023). "In conclusion, our study revealed that EJ, a sesquiterpene lactone from EL, could act as a STAT3 degradation agent to inhibit cancer cell metastasis and is expected to be applied in cancer therapy." (PMID 37049904, 2023). "This suggests that STAT3 may be an attractive cancer therapeutic target, with a large therapeutic index." (PMID 38022653, 2023). "Dysregulation of HRAS and STAT3 pathways is frequently observed in several cancers." (PMID 37298367, 2023). "STAT3 is crucial for controlling CSCs of cancers such ovarian cancer, HCC, breast cancer, colorectal cancer, glioblastoma, lung cancer, and prostate cancer, given its significant function in preserving the self-renewal and differentiation of embryonic stem cells (ESCs)." (PMID 37373393, 2023). "Future studies examining the expression and functions of STAT5 and STAT3 proteins in various cancers may sort out the relationships between STAT proteins." (PMID 37369132, 2023).
cancer (continued). "Thus, the targeting NFκB/STAT3-dependent EMT-TFs—particularly TWIST activation—offer a great promise as one of the possible targets in cancer pharmacotherapy." (PMID 37460910, 2023). "HIC1 is downregulated in PCa and act as a STAT3 inhibitor, which may be a promising target of cancer research and treatment for PCa." (PMID 36741321, 2023). "In addition, elevated IL-6 levels hyperactivate the JAK/STAT3 signaling pathway, as has been observed in many cases of hematopoietic or solid malignancies." (PMID 37240202, 2023). "Therefore, our findings together with the previous findings provide an excellent opportunity to develop novel anti-cancer drugs by inhibiting the activities of STAT3, Pol I, and Pol III products." (PMID 36656267, 2023). "Thus, it is necessary to further investigate and understand the role and regulatory mechanism of STAT3 in cancer cell proliferation and survival to develop effective anti-cancer drugs." (PMID 36656267, 2023). "STAT3 is an oncogenic transcription factor frequently activated in many types of cancer." (PMID 37887406, 2023). "As soon as direct STAT3 inhibitors reach the market, a rational combination for the pharmacologic treatment of cancer patients should include a STAT3 inhibitor to prevent and or reverse ADR and thereby increase the efficacy and duration of the therapeutic regimen." (PMID 36902166, 2023). "AKT and STAT3 signalling play a key role in cancer cell growth." (PMID 37907500, 2023). "It is known STAT3 collaborates with NF-κB to promote cancer development and progression." (PMID 36902125, 2023). "Moreover, STAT1 and STAT3 were shown to be generally high-expressed in pan-cancer myeloid cells, and STATs all had positive correlation with the infiltration of the majority of immune cells." (PMID 36968603, 2023). "Additionally, targeting the STAT3 signaling pathway has emerged as a promising therapeutic strategy for numerous cancers." (PMID 37238935, 2023). "Therefore, it is important to investigate the role of STAT3 in different types of tumors using pan-cancer analysis." (PMID 36977736, 2023). "BTK silencing significantly decreased the expression of the Janus kinase 2 (JAK2)/signal transducer and activator of transcription 3 (STAT3) and, in consequence, reduced cancer cell viability via the SRY-box transcription factor 2 (Sox-2) and BCL-XL genes and increased susceptibility to cisplatin." (PMID 36903645, 2023). "The present study may be useful for further development of STAT3 inhibitor-based therapy of cancer or age-related diseases." (PMID 36825563, 2023). "Furthermore, in silico study revealed that plumbagin can bind to cancer signaling proteins, namely PI3Kγ, AKT1/PKBα, Bcl-2, NF-κB, and Stat3, which play a key role in the pathogenesis of cancer." (PMID 37110873, 2023). "Other studies have also demonstrated that activation of PI3K/AKT promotes STAT3 phosphorylation and nuclear translocation, which facilitates the polarization of macrophages toward M2 and exerts immunomodulatory and pro-cancer effects through the secretion of a large number of mediators." (PMID 37081874, 2023). "A major transcription factor involved in cancer progression is STAT3." (PMID 36672229, 2023). "First, we analyzed the differential expression between normal tissues and pan-cancer tissues, and found that the expression of STAT3 was different in different tumors and different tissues, and there were significant differences between most tumors and normal tissues." (PMID 37724127, 2023). "Indeed, whereas most studies have identified STAT3 as positive regulator of cancer progression, other investigations pointed out that the IL-6/STAT3 axis can be a protective element in cancer." (PMID 37190183, 2023). "In addition to STAT3, the involvement of transcription factors such as NF-κB and C/EBPβ in EMT has also been described in human cancers, leading us to explore the possible association between IL-6 and NF-κB or C/EBPβ in HCT116 cells." (PMID 37047623, 2023).
cancer (continued). "Therefore, targeting the STAT3 protein through high-affinity ligands with the aim of reducing its levels or activity in cancers has noteworthy therapeutic potential." (PMID 37298475, 2023). "In addition, inhibition of the STAT3 molecule induced strong anti-cancer immunity leading to enhanced anti-cancer therapy." (PMID 36980527, 2023). "Since STAT3 dysregulation contributes to many human cancers and other human diseases." (PMID 36733714, 2023). "In addition, accumulating evidence has revealed that the STAT3 signaling pathway modulates DNA damage repair 18, 19, supporting the roles of STAT3 in cancer radioresistance." (PMID 37564211, 2023). "Third, the combination of PCSK9 inhibitors and Rapamycin could enhance the inhibition of the STAT3 signaling pathway, promote apoptosis, and reduce the potential proliferation and metastatic ability of malignant tumors." (PMID 37896137, 2023). "Aberrant regulation of STAT3 has been reported in nearly 70% of cancers." (PMID 37097001, 2023). "In addition to mediating the cancer cell-immune crosstalk via cancer cell-intrinsic signaling pathways, STAT3-mediated immune suppression also occurs within different immune cell types." (PMID 39872303, 2023). "Additionally, blocking STAT3 increases the proinflammatory mediators within cancer cells, which in turn can potentially induce DC activation." (PMID 39872303, 2023). "The relevance of the remaining hub genes identified by our analysis of dysbiosis and T. vaginalis dysregulated miRNAs (SMAD4, UBE2I, STAT3, CDC41 and YWHAZ) remains to be investigated in the clinical context of T. vaginalis, BV and associated cancer and pregnancy complications." (PMID 36985125, 2023). "In addition, it specifically inhibits STAT3 and retains the cellular response to cytokines with anti-tumor activity on different types of cancer cells including colorectal cancer, glioblastoma, multiple myeloma, and liver cancer cells." (PMID 38027032, 2023). "Analysis using the ‘Cancer Hallmark’ gene set indicated that the top pathways suppressed by JGT in SI rats were IFNα and IFNγ, and inflammatory responses and IL6/JAK/STAT3 signaling, that is, the same pathways that were activated in SI rats compared with GH rats." (PMID 36980301, 2023). "A time course study with IL-10-neutralized MDSCs supernatant on Dox resistant cancer cells, showed downregulated p-STAT3 expression as early as 60 mins post treatment, whereas, IL-6- neutralized supernatant has showed decreased p-STAT1 activation after 240 mins of treatment." (PMID 38304256, 2023). "Overall, these findings provided evidence that the dual inhibitors of IDO1 and STAT3 may offer a promising avenue for the development of highly effective drug candidates for cancer therapy." (PMID 37630387, 2023). "Evidence indicates that STAT3 is involved in cancer metastasis." (PMID 37846594, 2023). "Indeed, STAT3 is considered an oncogene, being hyperactivated in approximately 50% of all human cancers, with its hyperactivation correlating with enhanced tumor progression and poor prognosis." (PMID 38255152, 2023). "Candidate gene studies have implicated rs351855 (p.G388R) in cancer susceptibility, and subsequent mechanistic studies showed a gain of function of the mutant FGFR4 by binding transducer and activator of transcription 3 (STAT3)." (PMID 36823471, 2023). "Recent studies have also suggested that GSTO1 may be involved in the JAK/STAT3 signaling pathway, further highlighting its potential as a target for cancer therapy." (PMID 37047688, 2023). "Acacetin (20, 30 and 50 μM) also inhibits cancer cell proliferation and cell growth by reducing the phosphorylation of STAT3 in DU145 cells and then induces apoptosis by suppressing the expression of STAT3 target proteins, such as Bcl-2, Bcl-xL, Mcl-1, cyclin D1 and survivin." (PMID 37298192, 2023). "Cell–cell interaction between cancer cells and macrophages is crucial for STAT3 activation." (PMID 36260158, 2023).
cancer (continued). "It has been proven that isoorientin could suppress epithelial-to-mesenchymal processes and cancer stem-cell-like features by inhibiting the Wnt/β-catenin/STAT3 pathway in oral squamous cell carcinoma." (PMID 36678588, 2023). "The opposing roles of STAT3 in cancer may be explained by the existence of two alternatively-spliced STAT3 isoforms: the full-length STAT3α isoform (92 kDa) and the truncated STAT3β isoform (83 kDa)." (PMID 37097001, 2023). "The regulation of STAT3 activity could effectively suppress carcinogenesis, cancer development, and invasive behavior in TNBC." (PMID 37651362, 2023). "Our results suggest that targeting pS727 STAT3 may enhance anti-cancer immune responses and rescue the suppressed immunologic microenvironment in tumors." (PMID 37945711, 2023). "Inspired by the ability of CADs to induce rapid cytosolic acidification in cancer cells, we tested whether CADs could serve as STAT3 inhibitors." (PMID 36807142, 2023). "The IL-6/STAT3/VEGFA signaling pathway is activated in different cancers." (PMID 36720310, 2023). "Through the treatment of pro-nifuroxazide NP, the level of transcription factor pSTAT-3 was significantly decreased which could inhibit the phosphorylation of STAT-3, effectively inducing cancer cells apoptosis." (PMID 37143168, 2023). "In this sense, STAT3 has emerged as a promising target in cancer treatment." (PMID 38098005, 2023). "Furthermore, STAT3 and NF-κB are required for communication between cancer cells and their microenvironment, mainly with inflammatory/immune cells that infiltrate the tumors." (PMID 37731844, 2023). "In breast cancer cell lines, it was shown that Cycloguanil and its most promising analogue, NSC127159, were shown to inhibit Dihydrofolate reductase (DHFR), an established anti-cancer drug target whose inhibition disrupts folate metabolism and STAT3-dependent gene expression." (PMID 38146457, 2023). "However, STAT3 has multiple roles and STAT3 actions are context dependent, as shown in a study using cancer cells." (PMID 37846594, 2023). "In addition, IFN-λ acted together with related genes such as STAT1, STAT2, and STAT3 affecting the JAK-STAT signaling pathway to promote cancer progression." (PMID 37697300, 2023). "In summary, the study of the regulatory relationship between PI3K and STAT3 is of great significance to understand the development of cancer, and the inhibition of STAT3 expression may represent a breakthrough in the treatment of human tumors." (PMID 37724127, 2023). "However, with cancer, STAT3 becomes hyperactive and can increase cancer cells’ proliferation and survival, making it the target of cancer immunotherapy." (PMID 37241895, 2023). "In this study, a derivative of the natural marine compound ageladine A, compound 25, was found to act as a potential STAT3 inhibitor through STAT3-dependent reporters and cell-based screening strategies, which inhibited STAT3 transcriptional activity and cancer cell growth in the micromolar range." (PMID 37240202, 2023). "IL-6 binding to cancer cells is capable of initiating several mitogenic signaling cascades via activation of the PI3K/Akt, ERK/MAPK, and the JNK/STAT3 pathways, resulting in increased cancer cell survival, proliferation, malignant transformation and dedifferentiation, migration, and invasion." (PMID 38067195, 2023). "Aberrant STAT3 activation has been observed in a wide range of cancers such as lung cancer, colorectal cancer, breast cancer, melanoma, ovarian cancer, prostate cancer, hepatocellular carcinoma, pancreas cancer, leukemia and multiple myeloma, and plays a central role in immune regulation." (PMID 37073329, 2023). "Moreover, AOM/DSS-induced nuclear Trx-1 expression was suppressed in Txn1(KK81-82EE) mice, which inhibited STAT3 activation and cancer progression." (PMID 37771783, 2023).